COL1A1 (collagen type I alpha 1 chain)
Diseases named in the same sentence as COL1A1 in open-access papers (continued):
Sharing a sentence is not in itself a finding about the gene and the disease.
cancer (continued). "To identify potential therapeutic targets of those cancers and immune escape, we have collected more than forty representative immune checkpoint genes, including BTLA, CD200, TNFRSF14, NRP1, LAIR1 and so on, and we evaluated the relationship between expression of COL1A1 and immune checkpoint." (PMID 35789341, 2022). "Also, TargetScan database showed a binding site between miR-193a-5p and COL1A1, which encouraged us to further explore whether FBXL19-AS1 works in promoting cancer by indirectly regulating COL1A1 expression." (PMID 34399848, 2021). "In line with the oncogenic role of these genes, we observed a decrease in proliferation of H226 cells when either PDGFRB or COL1A1 were inhibited, additive to the effect achieved with GAS6 downregulation alone, supporting the existence of a SWINGN-dependent oncogenic hub in this cancer type." (PMID 32071317, 2020). "Previous studies have reported that COL1A1 and COL1A2 could enhance cancer progression." (PMID 31409759, 2019). "Besides COL1A1, serpin family E member 1 (SERPINE1), matrix metallopeptidase 9 (MMP-9) and matrix metallopeptidase 14 (MMP-14), were all drastically increased in cancer lesions as well." (PMID 29720137, 2018). "Moreover, our analysis indicates that LOX is likely co-expressed with MMP2, COL1A1 and SPARC, all of which contribute to initiating cancer metastasis and EMT, and that bisphosphonates inhibit MMP2 activity, COL1A1-driven osteoporotic fracture and SPARC-stimulated EMT." (PMID 27147578, 2016). "However, the expression levels of COL1A1 and COL1A2 in malignant tumors remain controversial." (PMID 27894325, 2016). "In addition, data mining results from The Comparative Toxicogenomics Database indicates that bisphosphonate down-regulates expression of LOX, MMP2, COL1A1 and SPARC, which means bisphosphonate may suppress cancer metastasis by targeting these four genes." (PMID 27147578, 2016). "In addition, fibroblasts (n = 1 068) were identified by COL1A1 and FAP, endothelial cells (n = 2 561) were positive for RAMP2 and CLDN5 expression, smooth muscle cells (n = 1 100) were defined by TAGLN and CNN1, and epithelial/cancer cells (n = 319) were labeled by KRT14 and KRT17." (PMID 40360503, 2025). "On the other hand, none of the dHCPPIs was the same for all cancer types studied, and five interactions were the same in at most seven different cancers (i.e., CAV1-CTNNB1, COL1A1-IGFBP3, LDHA-LDHB, PCNA-GAPDH, and PSMB7-PSMB3)." (PMID 36422095, 2022). "When looking into the CAF markers more specifically, COL1A1, ACTA2, and alpha-SMA are not significantly different in cancer tissues, compared to adjacent lung tissues, partially proving their roles may be allocated to the TME subgroup, not in whole cancer tissues or lung tissues." (PMID 39034310, 2024).
infection (36 papers, 2014 to 2025). The state of being infected such as from the introduction of a foreign agent such as serum, vaccine, antigenic substance or organism. "In concert with the elevated levels of collagenases in response to infection, COL1A1, which encodes the major fibril of type I collagen, was significantly down-regulated across the course of the infection." (PMID 34805001, 2021). "It is possible that infection can cause changes in ALP or COL1A1 expression at other stages during differentiation." (PMID 32493723, 2020). "For instance, Collagen Type I Alpha 1 (COL1A1) is up-regulated in the mastitic mammary gland and associated with tissue damage and repair during the later stages of infection." (PMID 27459697, 2016). "This was accompanied by an increase in tubular injury markers, such as Havcr1, Col1a1 and Col1a2 which encode KIM-1 and type 1 and 2 collagen, respectively; markers that were also identified in our study with PbA infection." (PMID 40661967, 2025). "The same applies to osteogenesis-related genes such as osteocalcin and Collagen Type I Alpha 1 (Col1A1), which also show down-regulation after infection." (PMID 39467689, 2024). "FXR deficiency also didn’t influence the content of hydroxyproline and the mRNA level of Col1a1 in livers of mice with infection." (PMID 35930537, 2022). "In sheep, the TGFB1 and COL1A1 genes were upregulated during the acute phase of infection in peripheral blood mononuclear cells (PBMC), and at later stages in liver tissue (8 wpi)." (PMID 34122452, 2021). "Expression of COL1A1 was significantly decreased following infection with 8325-4 and 8325-4heat-killed." (PMID 34480054, 2021). "The Euclidean distances between protein aggregation profiles indicated that, while ITGB1 and collagen (COL1A1) or fibronectin (FN1) became gradually distant during infection, ITGB1 and CD63 became closer." (PMID 32041945, 2020). "Thirty days after infection with LCMV strain clone 13 Sod1−/− mice showed fibrotic processes in the liver tissue as indicated by increased Col1a1 mRNA expression." (PMID 26588782, 2015). "A similar increase of Col1a1 expression was observed also upon infection with the acute LCMV strain ARM." (PMID 26588782, 2015). "Robust changes in expression of several genes was evident 7 days post-infection; expression of Col1a1, Col1a2, Col3a1, Mmp2, Mmp9 and Lox was significantly increased while expression of Timp3 was significantly decreased." (PMID 24950301, 2014). "The contribution of stellate cells—whose markers of the activated form are Acta2, Col1a1, Tagln, Col1a2, Col3a1, Sparc, and Rbp1—changed significantly only during infection with C. sinensis compared to the control (pairwise Kruskal–Wallis test with Benjamini–Hochberg correction, Padj = 0.030)." (PMID 39652576, 2024). "Researchers have identified increases in the expression of several genes (SMAD3, SMAD4, COL1A1) related to TGF-β and associated with evidence of fibrosis-associated cell types, including fibroblast and stellate cell lines, in acute stages of infection in sheep." (PMID 29970179, 2018). "The up-regulated expression of COL1A1 and ITIH4 in the mastitic mammary gland may be associated with tissue damage and repair during late stages of infection." (PMID 25273983, 2014). "Infection of HLF1 or WI38 fibroblast cell lines with RV-A16 or RV-A2 induced upregulation of TGFB1, MMP9, COL1A1, ADAM33, CHI3L1, LTC4S, and ACTA2." (PMID 37773065, 2023). "The result showed that some mesenchymal markers, such as COL1A1, α-SAM, and TAGLN, faded and endothelial markers PROX1 and PDPN increased starting at the fourth day post-infection." (PMID 34936683, 2021). "HRV16 infection also led to a significant increase in expression of genes involved in EMT (e.g., COL1A1, MMP9, SNAI1, and ZEB2) and growth factors (e.g., ~ fourfold for EGF and FGF2, and to a lesser extent TGFB1)." (PMID 34140575, 2021).
infection (continued). "Expression of ECM genes such as Fn-EDA and Collagen I (Col1a1) was upregulated after GHMT infection, but downregulated 12 days post infection." (PMID 26354680, 2015). "In addition, immunofluorescence staining demonstrated that ivermectin significantly reduced COL1A1 and TGF-β protein expression in primary HSCs after infection, further corroborating its antifibrotic effects." (PMID 41220567, 2025). "Also, whereas collagen proteins were downregulated during infection of HFFF-TERTs, the same proteins were upregulated in THP-1s (COL1A1, COL1A2, COL3A1, COL5A1, and COL12A1)." (PMID 38065956, 2023). "However, two genes (COL1A1 and COL1A2) showed decreasing expression pattern after infection in our study." (PMID 30584247, 2018). "Similarly, a reduction in COL1A1 expression was seen, together suggesting both a reduction in matrix formation and increased osteocyte-mediated matrix degradation, consistent with our recent observations in PJI patient bone, ex vivo human bone and primary osteocyte models of infection." (PMID 34805001, 2021). "In our in vitro model of osteoblast lineage infection, we first observed that internalized S. aureus 8325-4 (a reference lab strain) significantly impacted RUNX2 and COL1A1 expression compared to its non-internalized counterpart 8325-4∆fnbAB (with deletion of fnbA and fnbB)." (PMID 34480054, 2021).
connective tissue disorder (25 papers, 2011 to 2025). A disease involving the connective tissue. "As OI is a connective tissue disorder very often caused by dominant mutations in the genes COL1A1 and COL1A2, gene silencing through RNA interference is a promising field." (PMID 38398378, 2024). "Analysis of genes causing connective tissue disorders according to ACGS guidelines revealed four P/LP variants in COL1A1, COL6A1, FKBP14, and ALPL." (PMID 39298385, 2024). "OI is a rare, inherited systemic connective tissue disease caused by mutations in COL1A1 or COL1A2 that lead to varying degrees of bone fragility based on the abundance of these collagen types in healthy osteogenic tissue." (PMID 37623368, 2023). "It is an autosomal dominant connective tissue disease causing defects in collagen, associated with two genes, COL1A1 or COL1A2." (PMID 35162892, 2022). "Recently, many studies have indicated SNPs in the COL1A1 gene, which have been associated with an increased risk of several complex connective tissue disorders, such as SD, ATR, AT, and ACLR." (PMID 34356072, 2021). "Dominant inherited mutations in COL1A1 are known causes of connective tissues disorders such as OI." (PMID 27484908, 2016). "Both collagen 1A1 (COL1A1) and fibrillin-1 (FBN1) are associated with connective tissue diseases, and the change in their expression aggravates vessel damage." (PMID 38715006, 2024). "Col1a1 and Col3a1 are used as markers for valvular integrity, cardiac fibrosis, and connective tissue disease." (PMID 33322681, 2020). "Classical Ehlers–Danlos syndrome (cEDS) is a connective tissue disorder mainly caused by heterozygous COL5A1 or COL5A2 variants encoding type V collagen and rarely by the p.(Arg312Cys) missense substitution in COL1A1 encoding type I collagen." (PMID 32720758, 2020). "No variants could be associated with monogenic connective tissue disorder clinically associated with CI (except the case with COL1A1 that could not be resolved)." (PMID 39298385, 2024). "Notably, of the 29 children with nFTS with dysmorphic features resembling connective tissue disorders, 7 had VUSs of genes known to be related to connective tissue (BMP4, MATN3, COL2A1, COL11A1, COL1A1, COL1A2, and COL6A3)." (PMID 40524006, 2025). "Previous molecular investigations of the patient, all with negative results, included molecular genetic analysis of COL1A1 and COL1A2 on cDNA for the suspicion of arthrochalasis EDS, and an NGS panel for 101 connective tissue disorders." (PMID 31731524, 2019).
bone disorder (10 papers, 2015 to 2025). "OI is a brittle bone disorder caused by mutations in COL1A1 or COL1A2 in over 90% of cases; with mutations in many other genes, including SERPINF1, responsible for the other 10% of cases." (PMID 27056980, 2016). "The novel collagen fragments presented, some of which are COL1A1-specific, provide new insights into the pathways of collagen degradation and support the clinical potential of monitoring collagen peptide fragments in bone disorders." (PMID 41216609, 2025). "Notably, three patients had VUS in COL1A1, LRP5, and COL1A2 that matched their suspected monogenic bone disorders." (PMID 37076969, 2023).
genetic disorder (10 papers, 2012 to 2025). "Hence, the phenotype of Col1a1-Trps1 mice recapitulates main features of Dspp knockout (KO) mice and the human genetic disorder DGI." (PMID 22508542, 2012).
skeletal dysplasia (10 papers, 2018 to 2025). Any Mendelian diseases that affects growth and development of the skeleton. "During her first pregnancy, a c.1777G>A mutation in the COL1A1 gene was detected in the fetus who exhibited skeletal dysplasia, thus the family chose to terminate her pregnancy." (PMID 35463886, 2022). "At the first pregnancy, a c.1777G>A mutation in the COL1A1 gene was detected in the fetus who exhibited skeletal dysplasia." (PMID 35463886, 2022). "Skeletal dysplasia (SD) is one of the most common inherited neonatal disorders worldwide, where the recurrent pathogenic mutations in the FGFR2, FGFR3, COL1A1, COL1A2 and COL2A1 genes are frequently reported in both non-lethal and lethal SD." (PMID 34789231, 2021).
kidney disease (8 papers, 2019 to 2025). "While these findings generally suggest a reduced degradation of COL1A1 in fibrosis, the inconsistencies observed in the relationship between COL1A1 peptides and kidney disease are obvious and unexplained." (PMID 39740102, 2025). "Transcript levels of Col1a1, Col3a, and Fn1 were higher in the kidney disease models, but they were lower in Acss2–/– mice with kidney injury." (PMID 38051585, 2023). "Notably, among these abnormally expressed proteins, 19 proteins were reported as kidney disease markers (Ada, Ambp, Anxa1, B2m, Camp, Col1a1, Cp, Ggt1, Glb1, Lgfbp7, Lifr, Lpl, Plau, Ptgds, S100a8, Serpinc1, Serpina3k, Tff1, and Vtn) (highlight in green)." (PMID 31708494, 2019).
musculoskeletal disorders (6 papers, 2017 to 2024). "Comparing our results with eight other recent studies on fetal structural abnormalities showed that FGFR3 and COL1A1 are the most common pathogenic genes in musculoskeletal disorders, suggesting a strong genotype-phenotype correlation." (PMID 37880672, 2023). "Literatures have demonstrated that COL1A1 rs1800012 polymorphism contribute to the risk of musculoskeletal diseases." (PMID 29088884, 2017). "The COL1A1 gene encodes the α1 chain of type I collagen, and the data reported so far demonstrate that its polymorphic variants may affect biomechanical properties of bones, muscles, and tendons, and contribute to musculoskeletal disorders." (PMID 39684930, 2024). "We observed that MYH7, RYR1, FBN1, TNNT1, MYBPC1, COL1A1, and CHRNB1 were related to musculoskeletal disorders." (PMID 38658807, 2024).
liver (3 papers, 2023 to 2025). "A group of ColClusters in gastrointestinal (GI) tumors were enriched for tumors with lower levels of aneuploidy, high expression of fibrillar collagens including COL1A1, and yet also had relatively short overall survival, including COAD-C1, PAAD-C1, and STAD-C1." (PMID 37414817, 2023). "However, panose treatment failed to alleviate liver injury at this stage, as demonstrated by comparable plasma ALT and AST levels, Sirius Red–stained liver fibrosis scores, and mRNA expression of fibrotic markers (α-Sma, Col1a1, and Timp1) between PBS and panose treatment groups." (PMID 40478727, 2025). "In addition, we confirmed that the mRNA expression of COL1A1 and TGF-b, factors affecting the liver fibrosis process, was upregulated by THA treatment but decreased by Rh2 treatment." (PMID 40431422, 2025).
Metabolic Disorders (3 papers, 2025). "Our study provides novel insights into the genetic associations of COL1A1 and COL1A2 polymorphisms with BMD and metabolic disorders." (PMID 40507792, 2025). "The aim of this study was to evaluate the association between rs1107946 and rs1800012 polymorphisms in COL1A1, as well as rs42524 in COL1A2, with BMD and the risk of metabolic disorders in postmenopausal women." (PMID 40507792, 2025). "Genetic variations in the COL1A1 and COL1A2 genes have been linked to bone mineral density (BMD) and metabolic disorders." (PMID 40507792, 2025).
Neurological disorders (2 papers, 2019 to 2025). "In cultured human HSCs, sodium valproate, a broad class I and II HDAC inhibitor also used in the clinic to treat a variety of neurological disorders, demonstrated antifibrotic properties by inhibiting the expression of Col1a1 and TGFβ1 without causing toxic effects." (PMID 31117267, 2019).
intestinal diseases (1 paper, 2022). "In addition, alpha-fetoprotein (AFP), IGK protein, and collagen alpha-1 (I) chain precursor (COL1A1) were also used as biomarkers for some intestinal diseases." (PMID 36204290, 2022).
mitochondrial disease (1 paper, 2025). "A combined urinary biomarker panel—including stress markers (GDF15, CYCS, and PRDX2), immune effectors (MPO and C4A), ECM proteins (COL1A1 and CCN2), and selected amino acids—could support diagnosis, patient stratification, and longitudinal monitoring in mitochondrial disease." (PMID 41373442, 2025).
COL1A1 also shares sentences with these, for which no sentence is quoted: achondroplasia (4 papers); idiopathic pulmonary fibrosis (4); inflammation (4); medulloblastoma (4); adenocarcinoma (3); cardiovascular diseases (3); Ewing sarcoma (3); head and neck squamous cell carcinoma (3); hypertrophy (3); lung squamous cell carcinoma (3); Nephropathy (3); alcoholic liver diseases (2); bladder urothelial carcinoma (2); campomelic dysplasia (2); cardiac arrhythmias (2); cardiac disease (2); dilated cardiomyopathy (2); endometrial stromal sarcoma (2); Hernia (2); Hip dysplasia (2); immune diseases (2); inflammatory myofibroblastic tumor (2); keratoconus (2); leiomyosarcoma (2); lung disease (2); malignant mesothelioma (2); mesenchymal neoplasm (2); myopathy (2); Parkinson disease (2); postmenopausal osteoporosis (2).
A further 162 diseases each share a sentence with COL1A1 in 2 papers or fewer.